CX3CL1 (C-X3-C motif chemokine ligand 1)
Diseases named in the same sentence as CX3CL1 in open-access papers (continued):
Sharing a sentence is not in itself a finding about the gene and the disease.
peritonitis (4 papers, 2015 to 2023). Inflammation of the peritoneum (tissue that lines the abdominal wall and covers most of the organs in the abdomen). "In conclusion, we provide evidence that mPGES-1-derived PGE2 contributes to the resolution of zymosan-induced peritonitis by reducing the expression of epithelial CX3CL1, which allows to reestablishing cellular homeostasis in the peritoneum." (PMID 33542207, 2021). "To validate mPGES-1-dependent CX3CL1 regulation, we exposed murine epithelial E0771 cells in vitro to medium supplemented with peritoneal lavages obtained from mice at day 6 of the peritonitis model." (PMID 33542207, 2021). "Conclusively, mPGES-1 contributes to terminate a zymosan-induced peritonitis by limiting epithelial expression of CX3CL1, thereby reconstituting the cellular composition of the peritoneal cavity." (PMID 33542207, 2021). "Inhibition of mPGES-1 apparently enhanced epithelial expression of CX3CL1, which adds to increase Mφ numbers in the peritoneal cavity during resolution of zymosan-induced peritonitis." (PMID 33542207, 2021). "The genetic manipulation of CX3CL1 signalling has to date led to contradictory findings in mouse models of peritonitis regarding its role in immune defence." (PMID 27549131, 2016). "The expression of ApoE mRNA was also significantly higher in Cx3cr1GFP/GFP peritoneal Mφs (prepared from thioglycollate-elicited peritonitis) when compared to WT-Mφs cultured for 24 h in the presence of CX3CL1 (Fig3F)." (PMID 25604058, 2015). "Thus, in contrast to the CX3CL1/CX3CR1 axis, Lyve1 levels in macrophages negatively correlated with PGE2 levels in the course of peritonitis, indicating that Lyve1 might have a pro-resolving function." (PMID 37998039, 2023).
renal carcinoma (4 papers, 2020 to 2024). A carcinoma arising from the epithelium of the renal parenchyma or the renal pelvis. "CX3CL1 is expressed in various renal cell types, including podocytes, endothelium, tubular epithelium, mesangial, and renal cancer cells." (PMID 37875838, 2023).
renal cell carcinoma (4 papers, 2022 to 2025). "Tsaur and his colleagues demonstrated that renal cells carcinoma of the chromophobe subtype had considerably reduced CX3CL1 gene expression relative to normal tissue, and that CX3CR1 and C-reactive protein were positively correlated." (PMID 37153002, 2023). "In a study using tissue from a patient with renal cell carcinoma, CX3CL1 in the red bone marrow of the spinal trabecular bone was shown to enhance the migration and invasive potential of renal cell carcinoma cells and to promote the metastasis of renal cell carcinoma to the spine." (PMID 40508161, 2025). "Finally, in order to evaluate the role of CX3CL1 in renal cell carcinoma cells, we then performed the cell proliferation assays." (PMID 37927470, 2023). "Renal cell carcinoma, a typical immune-excluded tumor, is considered to lack the expression of some chemokines related to T cell recruitment, such as CXCL9, CXCL10, CXCL11, CXCL13, CX3CL1, CCL2, and CCL5, in its TME, but the specific mechanisms underlying this lack of chemokines remain unclear." (PMID 36397015, 2022).
retinitis pigmentosa (4 papers, 2014 to 2025). Retinitis pigmentosa (RP) is an inherited retinal dystrophy leading to progressive loss of the photoreceptors and retinal pigment epithelium and resulting in blindness usually after several decades. "In retinitis pigmentosa models, CX3CL1-CX3CR1 signaling constrains this aberrant phagocytic activation; disruption of the pathway aggravates degeneration, whereas augmentation of soluble CX3CL1 preserves cone survival and visual function in vivo." (PMID 41394857, 2025).
status epilepticus (4 papers, 2014 to 2023). Status epilepticus is defined as a continuous seizure lasting more than 30 min, or two or more seizures without full recovery of consciousness between any of them. "Elevated CX3CL1 immunoreactivity has also been confirmed in the hippocampus 1 to 3 h after pilocarpine-induced status epilepticus in rats." (PMID 31818018, 2019). "The increased CX3CL1 levels decrease to control levels 3 days after status epilepticus." (PMID 31818018, 2019). "Moreover, both CX3CL1 and its receptor, CX3CR1, have been shown to be up-regulated in hippocampal neurons after pilocarpine-induced status epilepticus, a condition characterized by excessive glutamatergic excitation." (PMID 25161610, 2014).
synucleinopathy (4 papers, 2012 to 2025). A neurodegenerative disease that is characterized by the abnormal accumulation of aggregates of alpha-synuclein protein in neurons, nerve fibers or glial cells. "Evidence in transgenic models suggests a beneficial effect of microglial activity on clearance of proteins like Aβ and a detrimental effect on Tau modification, but the role of CX3CL1 signaling in α-synucleinopathies is less clear." (PMID 22919540, 2012). "Therefore, the decline of neuronal CX3CL1 expression is not specific to synucleinopathies but represents a general inflammatory response." (PMID 40842561, 2025).
systemic sclerosis (4 papers, 2018 to 2024). A chronic disorder, possibly autoimmune, marked by excessive production of collagen which results in hardening and thickening of body tissues. "Regarding this study, CX3CL1 appears to be associated with progressive lung involvement in systemic sclerosis." (PMID 34208027, 2021). "In summary, this review aims to highlight the function of CX3CR1 and CX3CL1 (FKN) in systemic sclerosis." (PMID 39392260, 2024).
acute coronary syndrome (3 papers, 2012 to 2021). Signs and symptoms related to acute ischemia of the myocardium secondary to coronary artery disease. "Prior studies indicate that CX3CL1 levels are significantly increased in both chronic coronary artery disease and acute coronary syndromes." (PMID 24995121, 2014). "Prior studies of CX3CL1 in human subjects focused on cohorts with chronic coronary artery disease, or acute coronary syndromes." (PMID 24995121, 2014). "A recent study of patients with the acute coronary syndrome randomly assigned to colchicine (1.5 mg p.o.) showed that colchicine treatment was associated with significantly lower transcoronary levels of chemokine ligand 2 (CCL2), CCL5, and C-X3-C motif chemokine ligand 1 (CX3CL1) (p < 0.05)." (PMID 34829992, 2021).
alcohol use disorder (3 papers, 2020 to 2024). "The restored CX3CL1/CX3CR1 signaling, which is directly linked to the regulation of neuron–glial communication, offers potential protection against the neuroinflammatory conditions frequently observed in neuropsychiatric disorders, including alcohol use disorders." (PMID 39063614, 2024).
ANCA-associated vasculitis (3 papers, 2021 to 2024). "Many studies have also confirmed that FKN/CX3CL1 plays a key role in the pathogenesis of ANCA-associated vasculitis." (PMID 38937701, 2024).
bone metastasis (3 papers, 2018 to 2025). Transfer of a neoplasm from its primary site to bones. "Fractalkine (CX3CL1) is also associated with bone metastasis." (PMID 29930538, 2018).
cardiomyopathy (3 papers, 2019 to 2025). A disease of the heart muscle or myocardium proper. "Among these mediators, CX3CL1 has emerged as a dual-function chemokine, regulating inflammation and enhancing tissue repair while exacerbating T. cruzi-induced cardiomyopathy." (PMID 40936920, 2025). "In silico analysis showed several of these piRNAs were computationally predicted to target and potentially regulate expression of genes including SMAD2, EGR1, ICAM1, CX3CL1, and CXCR2, which have been implicated in parasite infection, pathogenesis, and various cardiomyopathies." (PMID 36936778, 2023). "In the context of cardiomyopathy induced by T. cruzi infection, the role of the CX3CL1/CX3CR1 axis was not explored until the late 1990s." (PMID 40936920, 2025).
cerebral infarct (3 papers, 2020 to 2022). "Exogenous CX3CL1 reduced ischemia-induced cerebral infarct size and neurological deficits in rats and these CX3CL1-induced neuroprotective effects mediated by microglia were long lasting, being observed up to 50 days after pMCAO in rats." (PMID 35955921, 2022).
co-infection (3 papers, 2015 to 2021). "In addition, CCL4, CXCL1, and CXCL2 expression in the co-infection group was highly significant, while CX3CL1 and XCL1 expression was equivalent to that in mock control." (PMID 33968006, 2021). "In addition, co-infection significantly regulated the mRNA expression of several chemokine and chemokine receptor genes, including CCL3 (1.62-fold), CX3CL1 (1.7-fold), CXCL16 (0.56-fold), CCR1 (2.23-fold), and CXCR4 (1.55-fold)." (PMID 25906258, 2015).
gestational diabetes (3 papers, 2015 to 2025). Carbohydrate intolerance first diagnosed during pregnancy. "In a study of pregnant women with and without gestational diabetes, serum CX3CL1 levels were similar between groups, but independently associated with HOMA-IR, suggesting effects on insulin signaling." (PMID 26393344, 2015).
HCMV infections (3 papers, 2017 to 2024). "Thus, CX3CL1-based FTP can be used as scaffold to create highly efficient and selective FTPs to control HCMV infections." (PMID 28251165, 2017).
inflammatory liver disease (3 papers, 2007 to 2026). "Previous studies indicated that increased levels of C-X3-C motif chemokine ligand 1 (CX3CL1) in the liver are associated with severe inflammatory liver disease." (PMID 35563788, 2022). "This review provides a systematic and critical examination of the multifaceted roles of the CX3CL1/CX3CR1 axis in liver diseases." (PMID 41716421, 2026).
migraines (3 papers, 2021 to 2024). "In contrast, CX3CL1 and t-Tau pose potential fluid biomarkers to study the pathophysiology of migraine and possibly inform clinical management." (PMID 38561692, 2024). "CX3CL1 in CSF is a novel potential fluid biomarker of migraine that is unrelated to the headache status." (PMID 38561692, 2024). "CX3CL1 in CSF thus provides a novel biomarker to study migraine pathophysiology in humans." (PMID 38561692, 2024). "CX3CL1 in CSF and serum t-Tau are novel potential fluid biomarkers in migraine, which may advance the investigation of migraine pathophysiology and inform clinical management." (PMID 38561692, 2024). "Concentrations of CX3CL1 were significantly increased both in the headache phase and interictally in CSF but not in serum compared with the non-migraine cohort (p = 0.014)." (PMID 38561692, 2024). "CX3CL1 in CSF but not in serum was significantly higher in migraine patients regardless of sample collection in the headache phase or interictally versus healthy controls." (PMID 38561692, 2024). "It remains to be clarified whether CX3CL1 concentrations differ between patients with migraines with and without aura." (PMID 38561692, 2024).
neuropathic pain (3 papers, 2018 to 2025). Chronic pain caused by damage to nerve fibers. "CX3CL1 is involved in paclitaxel-induced neuropathic pain (PINP), and blocking CX3CL1 significantly inhibits microglial activation and mechanical allodynia." (PMID 36713369, 2022). "EE can relieve neuropathic pain by reducing inflammatory mediators, such as proinflammatory cytokines (IL-1β, TNF-α, IL-6) and chemokines (CCL2, CCL3), among others, increasing anti-inflammatory substances (IL-10, Arg-1, CX3CL1) in the periphery and CNS." (PMID 40190342, 2025).
oral cancer (3 papers, 2023 to 2025). "CX3CL1 can induce the migration of oral cancer cells in a dose-dependent manner, and CX3CL1-positive nerves can attract CX3CR1-positive tumor cells, thereby promoting the development of perineural invasion (PNI) in OSCC patients." (PMID 41445742, 2025). "Although we have not determined the specific nociceptive mediators released by Schwann cells following TRPV4 activation, previous studies suggest the involvement of IL-6, CX3CL1, and TNF-α from Schwann cells in oral cancer pain." (PMID 40144515, 2025). "While simulation with CX3CL1 did not affect the proliferative capacity of oral cancer cells." (PMID 37082943, 2023).
osteosarcoma (3 papers, 2017 to 2023). A usually aggressive malignant bone-forming mesenchymal neoplasm, predominantly affecting adolescents and young adults. "CX3CL1 induced cell migration in human osteosarcoma cells via upregulating ICAM-1 expression mediated by CX3CR1/PI3K/Akt/NF-κBpathway44." (PMID 37770496, 2023). "For example, miR-485-5p retarded cell proliferation and metastasis via inhibition of CX3CL1 in osteosarcoma cells." (PMID 35692754, 2022). "Finally, we showed a clinical correlation between CX3CL1 expression and ICAM-1 expression as well as tumor stage in human osteosarcoma tissues." (PMID 28903329, 2017).
periodontal disease (3 papers, 2023 to 2025). "Regarding AZU and CX3CL1, these molecules have been strongly related to periodontal disease; however, no studies have been carried out associating them with the subgingival microbiota or as part of the effects produced in patients with prosthetic restorations." (PMID 36770741, 2023). "However, other molecules such as azurocidin (AZU) and fractalkine (CX3CL1) have recently been proposed as potential markers of periodontal disease." (PMID 36770741, 2023). "Accordingly, the severity of periodontal disease may thus affect salivary CX3CL1 and its receptors." (PMID 38590803, 2024).
prion disease (3 papers, 2014 to 2018). A transmissible disease that is caused by a protein that is able to induce abnormal folding of normal cellular proteins, leading to characteristic spongiform brain changes, which are associated with neuronal loss without an inflammatory response. "We have demonstrated that loss of Cx3cr1 results in an acceleration of onset of prion disease with three distinct prion strains (Chandler/RML, ME7 and MRC2) suggesting that intact Cx3cl1/Cx3cr1 signalling is partially protective in prion disease." (PMID 24655482, 2014). "To investigate the role of Cx3cl1/Cx3cr1 neuronal-glial cross talk in prion disease we inoculated female Cx3cr1-/- mice and Balb/c wild type controls intracerebrally with three different mouse-adapted prion strains." (PMID 24655482, 2014). "Our results show that for two mouse-adapted scrapie strains (Chandler/RML and ME7) and a mouse-passaged BSE strain (MRC2), Cx3cr1 deficiency shortens the incubation time thereby suggesting that Cx3cl1/Cx3cr1 signalling is partially protective in prion disease." (PMID 24655482, 2014). "To investigate the role of Cx3cl1/Cx3cr1 signalling in prion disease we infected Cx3cr1 null mice with three different strains of prions." (PMID 24655482, 2014). "Our data suggest a protective role for Cx3cl1/Cx3cr1 cross-talk in prion disease." (PMID 24655482, 2014). "Another microglia-related mechanism relevant to prion disease and influenced by ADAM10 is the Cx3cl1/Cx3cr1 signaling complex." (PMID 25654651, 2015).
pulmonary diseases (3 papers, 2018 to 2022). "Here, we examined the role of the CX3CR1/CX3CL1 biological axis in the pathogenesis of SSc associated lung disease." (PMID 30457999, 2018). "Moreover, we explored the association between serum concentrations of CX3CL1 and SSc associated pulmonary diseases and their severity." (PMID 30457999, 2018). "CX3CL1 is involved in various pathological processes, such as inflammatory response, and is closely related to the occurrence and development of such pulmonary diseases." (PMID 35186183, 2022). "The potential of CX3CL1 in the pathogenesis of fibrosing lung disease development was shown to be valid regardless of the origin of fibrosis—be it a primary (IPF) or secondary fibrotic process (HP, CTD-ILD, PS)." (PMID 34208027, 2021). "In order to evaluate the statistical significance of the CX3CL1 concentration difference between fibrotic pulmonary diseases (IPF and OFI) and non-fibrotic lung diseases (NFI) or the control group, we adopted logistic regression models." (PMID 34208027, 2021).
thymoma (3 papers, 2023 to 2024). A neoplasm arising from the epithelial cells of the thymus. "Moreover, higher expression of the ligand, CX3CL1, was associated with a higher M2 macrophage fraction in LUAD, TGCT (tenosynovial giant cell tumor), and THYM (thymoma) cancer types." (PMID 37771579, 2023). "Patients with hyperplasia and thymoma differed in several proteins, including IL-18R1, TRAIL, CCL23, CX3CL1, CD8A, IL-8, TNF-β, and CCL11." (PMID 39165841, 2024).
trauma (3 papers, 2017 to 2021). "In the light of this analysis, it is difficult to state whether GC modulation of the CX3CL1/CX3CR1 axis is a neuroprotective or neurotoxic therapeutic option in case of CNS trauma." (PMID 26927660, 2017). "Our results indicate that the neuroprotective effects of TNF-α-hNPCs in HI brain injury could be provided by stimulation of microglial CX3CR1 expression, as well as direct release of CX3CL1." (PMID 32403417, 2020).
type 1 diabetes (3 papers, 2022 to 2026). "Since β-cell secretory function is severely impaired in STZ-induced models of type 1 diabetes, the effect of CX3CL1 on insulin secretion would be difficult to identify in the present study." (PMID 35370759, 2022). "However, three genes are involved in the majority of these pathways: Cx3cl1 (immune and inflammatory reactions) and H2-Aa and H2-Ab1 (various disease, immune system, and type I diabetes mellitus)." (PMID 38483771, 2024).
unstable angina pectoris (3 papers, 2021 to 2025). "In clinical studies, serum levels of CX3CL1 is associated with cardiovascular diseases such as carotid artery stenosis, unstable angina pectoris, and systolic heart failure." (PMID 34460437, 2021). "Soluble CX3CL1 was significantly elevated in unstable angina pectoris patients with ruptured plaques." (PMID 40508161, 2025).
acute GVHD (2 papers, 2024 to 2026). "The high expression of CX3CR1 on the surface of CD8+T cells and the overexpression of its ligand CX3CL1 in the intestinal mucosa of patients with acute GVHD suggest the critical role of the CX3CR1/CX3CL1 axis in intestinal infiltration and damage during acute GVHD." (PMID 39840040, 2024). "In contrast, elevated IL-6, IL-17A, PAI-1, IL-10, CX3CL1, CXCL1, and CCL4 levels were prognostic for quiescent cGVHD compared with patients with resolved acute GVHD only." (PMID 41798937, 2026). "Blocking CX3CL1 can effectively diminish the infiltration of alloreactive CD8+T cells in the intestine and alleviate the apoptosis of intestinal crypt cells, providing a new strategy for the treatment of intestinal damage in acute GVHD." (PMID 39840040, 2024).
acute liver failure (2 papers, 2019 to 2021). Rapid deterioration of liver function causing encephalopathy and coagulopathy. "In the current study, we present novel data indicating that neuron-specific knockout of TGFβR2 attenuated the expression of CCL2, increased CX3CL1 expression, inhibited microglia activation, and reduced neurological deficits during acute liver failure." (PMID 30940161, 2019). "TGFβ1 is released into the circulation after acute liver failure and binds TGFβR2 in neurons, resulting in increased CCL2 expression and decreased CX3CL1 expression leading to microglial activation." (PMID 30940161, 2019).
anaplastic astrocytoma (2 papers, 2022 to 2023). "In another study, the expression of CX3CL1 was inversely correlated with patient overall survival with the uppermost scores of CX3CL1 expression in grades 3–4 tumors: oligodendrogliomas, anaplastic astrocytomas, and GBM." (PMID 37190507, 2023).
ankylosing spondylitis (2 papers, 2023 to 2024). An autoimmune chronic inflammatory disorder characterized by inflammation in the vertebral joints of the spine and sacroiliac joints. "More than that, another study reported increased CX3CL1 in ankylosing spondylitis, leading to elevated expression of M1-type macrophage markers and inflammatory factors that promote osteoclast differentiation." (PMID 39511608, 2024).
astrocytoma (2 papers, 2013 to 2022). "On the other hand, a negative-regulatory mechanism of constitutiveCX3CL1 production was suggested by the finding that basal CX3CL1 production inhuman astrocytomas was reduced by tumor growth factor beta (TGFβ)." (PMID 23627909, 2013).